CX3CR1 (C-X3-C motif chemokine receptor 1)
Diseases named in the same sentence as CX3CR1 in open-access papers (continued):
Sharing a sentence is not in itself a finding about the gene and the disease.
glioma (continued). "Bone marrow-derived CCR2+/CX3CR1+ cells adopt an immune suppressive cell phenotype when cultured with glioma-derived factors." (PMID 36685592, 2022). "KR158B, KR158B CCL2 KD or KR158B CCL7 KD glioma cell lines were implanted in Ccr2+/RFP/Cx3cr1+/GFP mice, and flow cytometry analysis of tumors and bone marrow was conducted 4.5 weeks post-implantation." (PMID 36685592, 2022). "While these previous findings established that CCR2+/CX3CR1+ MDSCs utilize CCR2 to traffic into the glioma microenvironment, it is unclear what chemokines drive this CCR2-dependent migration." (PMID 36685592, 2022). "We established that bone marrow and glioma-associated CD45high, CD11b+, Ly6Chi/Ly6G- cells co-express CCR2 and CX3CR1." (PMID 36685592, 2022). "The lack of effect observed following the implantation of individual CCL2 or CCL7 knockdown gliomas suggested a potential chemokine ligand redundant mechanism utilized by the KR158B cells to recruit CCR2+/CX3CR1+ cells to the TME." (PMID 36685592, 2022). "To directly establish if CCR2+/CX3CR1+ cells present within KR158B gliomas are sourced from the bone marrow we generated chimeric mice harboring Ccr2WT/RFP/Cx3cr1WT/GFP bone marrow cells." (PMID 36685592, 2022). "In conclusion, we determined that CCR2 and its cognate ligands are prominent regulators of the recruitment of a CCR2+/CX3CR1+ immune suppressive cell to gliomas." (PMID 36685592, 2022). "CCL2 and CCL7 are produced, at least in part, by glioma cells and our study indicates that CCL2 and CCL7 function in a redundant manner to induce the migration of CCR2+/CX3CR1+ M-MDSCs into the glioma microenvironment." (PMID 36685592, 2022). "To test the concept that CCL2 and CCL7 drive the recruitment of CCR2+/CX3CR1+ cells into the glioma microenvironment, we took a combinatorial targeting approach in vivo." (PMID 36685592, 2022). "Conversely, there was a significant reduction (p=0.003) from mean 25.8% to mean 10.8% glioma infiltrating CCR2+/CX3CR1+ cells when comparing KR158B + IgG vs. CCL7 KD + αCCL2 antibody arms." (PMID 36685592, 2022). "CCR2+/CX3CR1+ cells are also reduced within KR158B gliomas upon combination targeting of CCL2 and CCL7." (PMID 36685592, 2022). "Taken together with our previous data, we posit that this significant difference in survival between low and high expressors is due in part to an elevated level of recruitment of immunosuppressive CCR2+/CX3CR1+ cells into the glioma microenvironment." (PMID 36685592, 2022). "Further studies will be necessary to better understand direct and indirect mechanisms whereby CCR2+/CX3CR1+ M-MDSCs disrupt T cell function and dampen immune responses in the context of glioma." (PMID 36685592, 2022). "This study investigated the T cell suppressive function and chemokine ligand dependency by which CCR2+/CX3CR1+ M-MDSCs traffic into the glioma microenvironment." (PMID 36685592, 2022). "In contrast, macrophages in glioma TME with CX3CR1 expression were differentiated from CX3CR1lo peripheral monocytes entered the cranial cavity, which highly express CD45 and CCR2." (PMID 34211978, 2021). "CX3CL1 and CX3CR1 constitute the next chemokine ligand/receptor axis that plays an important role in glioma development." (PMID 32456359, 2020). "The glioma groups with high expression of WNT5a presented high levels of CX3CR1, connexin 43 (CX43), CD163, and IBA-1, suggesting that the GB-infiltrating microglial cells are activated, which represent the M2-like phenotype." (PMID 30123112, 2018). "The relative contribution of these populations in glioma progression was investigated in a genetically engineered mouse model, in which the chemokine CX3CR1/CX3CL1 signaling was ablated in both microglia and inflammatory monocytes." (PMID 29594035, 2018). "Patch-clamp recordings were performed in GFP+ cells of acute brain slices from glioma bearing Cx3cr1+/GFP mice, which comprise GAMs, dendritic cells, and NK cells." (PMID 29286001, 2017).
glioma (continued). "P2RY12 had a significant likelihood for co-occurrence with the microglia markers Iba-1 and CX3CR1 in GBM, and CX3CR1, CD11b in low grade glioma." (PMID 28073370, 2017). "In the context of glioma, CXCL12/CXCL12-receptor (CXCR4/CXCR7) autoregulatory signaling has been demonstrated to be important for glioblastoma survival and angiogenesis, while CX3CL1/CX3CR1 axis signaling in glioma cells controls glioma cell invasion." (PMID 28380429, 2017). "GL261/CX3CR1 revealed the close contact between microglia and glioma cells, from imaging techniques that present many advantages." (PMID 26856327, 2016). "The present GL261/CX3CR1 glioma model also allowed imaging of microglial cells present in tumor areas for analysis of morphology and cell density." (PMID 26856327, 2016). "Regarding gliomas, the TgH(CX3CR1-EGFP) mouse strain was used to investigate aspects of tumor biology, like the role of CX3CR1 receptors in malignant glioma and a preclinical rationale for the development of stroma-directed glioma therapies in children." (PMID 26856327, 2016). "The GL261/CX3CR1 mouse model reported here is a valuable tool for imaging of microglial cells during glioma growth, either in fixed tissue sections or living animals." (PMID 26856327, 2016). "In our model of glioma, we chose the TgH(CX3CR1-EGFP) mouse line, based on immunocompetent animals engineered to show fluorescent microglial cells." (PMID 26856327, 2016). "CCR2+ cells were detected in all 17 glioma tissue samples, and CX3CR1+ cells were found in 12 of the 17 glioma tissue samples." (PMID 27602954, 2016). "All TgH(CX3CR1-EGFP) immunocompetent mice (n = 24) developed brain tumors within 3 to 18 days after intracortical injections of mCherry-GL261 glioma cells." (PMID 26856327, 2016). "The present work evaluated a GL261/CX3CR1 model, dedicated to study microglial interaction with glioma tumors." (PMID 26856327, 2016). "First, our GL261/CX3CR1 model allowed imaging of microglia and glioma cells, easily discriminated by specific fluorescences." (PMID 26856327, 2016). "Here, we show that loss of CX3CR1/CX3CL1 signaling in tumor-associated microglia and monocytes results in an increased incidence of GBM formation with shorter tumor latency in glioma-bearing mice." (PMID 25987130, 2015). "Deletion of Cx3cr1 from the microenvironment resulted in increased tumor incidence and shorter survival times in glioma-bearing mice." (PMID 25987130, 2015). "We first hypothesized that glioma cells induce the differentiation process of CCR2+/CX3CR1+ MDSCs by secreting soluble factors that trigger M-MDSC differentiation." (PMID 39272914, 2024). "For instance, the disease-associated microglia (GAMs in glioma, ischemic-associated MG in MCAO, and DAM and IRM in SAH exhibit a decrease in several microglial core genes such as CX3CR1 and TMEM119, a high presence of inflammatory signatures, and an upregulation of distinct proliferation markers." (PMID 38665919, 2024). "We also found that CCR2+/CX3CR1+ M-MDSCs express iNOS in the glioma microenvironment and inhibition of NOS with L-NMMA could recover in vitro proliferation of CD8 T cells, but not CD4 T cell proliferation." (PMID 39272914, 2024). "CX3CR1 labels a specific CD8 +T cell population in the circulation of grade 4 glioma patients." (PMID 38127790, 2023). "To evaluate whether KR158B tumor cells are active contributors in the recruitment of CCR2+/CX3CR1+ cells, we tested whether glioma cells produced and secreted CCL2 and CCL7." (PMID 36685592, 2022). "On the other hand, there are studies demonstrating that the CX3CR1 gene could be regulated through DNA methylation in human glioma tumors, myeloid cells and CD8+ T cells." (PMID 36175906, 2022). "CX3CR1-mediated macrophage infiltration into gliomas has been confirmed in patient tissue." (PMID 35008294, 2021).
glioma (continued). "Moreover, glioma monocytes and macrophages can be identified based on the expression of Ly6c, Ccr2, Cx3cr1, Cd64, Mertk, Cd45, F4/80, Ccr7 and transcription factor Nr4a113." (PMID 32555306, 2020). "Furthermore, analysis of CX3CL1 and CX3CR1 expression in human glioma surgical samples with different histological degrees demonstrated that both ligand and receptor were present in most specimens, at the mRNA and protein levels." (PMID 32456359, 2020). "However, dysregulation of the fractalkine/CX3CR1 axis is correlated with malignancies of the central nervous system, such as gliomas and neuroblastoma." (PMID 28903329, 2017). "Therefore, we implanted red fluorescent protein-expressing glioma cells into brain slices from CX3CR1-GFP transgenic mice to track the movement and interaction of microglia with tumor cells during the culture phase." (PMID 26673818, 2016). "First, we confirmed that EGFP-positive cells of the GL261/CX3CR1 glioma model express Iba1." (PMID 26856327, 2016). "In conclusion, GL261/CX3CR1 is a valuable model for studies about glioma-microglia interactions." (PMID 26856327, 2016). "First, mCherry-GL261 glioma cells were implanted in the brain cortex of TgH(CX3CR1-EGFP) mice." (PMID 26856327, 2016). "The use of organotypic slice cultures allowed us to generate gliomas in a monocyte-free environment, where we demonstrated that loss of Cx3cr1 in microglia had no impact on glioma growth." (PMID 25987130, 2015). "Our data demonstrate that while increasing monocyte infiltration and tumor-promoting effects, loss of Cx3cr1 has no impact on microglia/macrophage accumulation in peri-tumoral areas in vivo or in organotypic slice cultures of gliomas ex vivo." (PMID 25987130, 2015). "Here we demonstrated that loss of Cx3cr1 in the host microenvironment resulted in increased accumulation of bone marrow-derived Ly6-Chigh “inflammatory” monocytes in GBM, in contrast to microglia in low-grade gliomas." (PMID 25987130, 2015). "In both datasets, CCR1 and CX3CR1 expression strongly correlated with the “macrophage” and “myeloid cell” signatures, while the two receptors were virtually absent from other cell types, unsurprisingly pointing to their key role in immune cell recruitment and function in gliomas." (PMID 35008294, 2021). "Therefore, using CX3CR1 as a microglia marker is reasonable under physiological conditions but a strong pathological stimulus like glioma progression could affect expression and should be further examined." (PMID 33375505, 2020). "Our previous work highlighted the presence of a population of myeloid cells in the glioma TME that expresses the chemokine receptors CCR2+ and CX3CR1+." (PMID 39272914, 2024). "This study evaluated the mechanism of CCR2+/CX3CR1+ M-MDSC differentiation and T cell suppressive function in murine glioma models." (PMID 39272914, 2024). "CX3CR1 was also highly expressed in ccRCC, ranking third among solid tumors behind myeloid-rich glioblastoma multiforme (GBM) and lower-grade glioma (LGG)." (PMID 38618956, 2024). "Recombinant and glioma-derived CCL2 and CCL7 induce the migration of CCR2+/CX3CR1+ MDSCs with similar efficacy." (PMID 36685592, 2022). "We have previously reported that three populations of myeloid cells are identified in the glioma microenvironment according to their expression of chemokine receptors CCR2 and CX3CR1." (PMID 36685592, 2022). "While these prior studies clearly support targeting CCR2+/CX3CR1+ cells as a means to treat gliomas, a greater appreciation of the immune suppressive and migratory properties of this CCR2+/CX3CR1+ cell population is needed." (PMID 36685592, 2022). "By analyzing the glioma data in the TCGA database, the expression level of SPI1 displayed a significant positive correlation with target genes (CX3CR1: r = 0.53; CSF1R: r = 0.876; IRF8: r = 0.678)." (PMID 34434898, 2021).
glioma (continued). "As a special member of glioma TME, microglia are recruited to lesions through CX3CL1/CX3CR1 chemokine channel, while peripheral monocyte-macrophages through the MCP-1/CCR2 channel." (PMID 34211978, 2021). "This study reported that glioma cells overexpress CX3CL1, which is responsible for the recruitment of CX3CR1-expressing microglia and macrophages." (PMID 35008294, 2021). "The model comprises a fluorescent glioma cell, mCherry-GL261, that was implanted in the cortex of TgH(CX3CR1-EGFP) mice with fluorescent microglia." (PMID 26856327, 2016). "The animal model associates the following cell types: 1- mCherry red fluorescent GL261 glioma cells and; 2- EGFP fluorescent microglia, present in the TgH(CX3CR1-EGFP) mouse line." (PMID 26856327, 2016). "To study the functional role of CX3CR1/CX3CL1 signaling in GBM, we used a genetically engineered mouse model (GEMM) of adult PDGFB-driven gliomas, which is based on RCAS/Tv-a, a somatic cell-specific gene transfer system." (PMID 25987130, 2015). "In this study we abrogated CX3CR1/CX3CL1 signaling in both microglia and inflammatory monocytes and studied the effects on glioma growth and on the behavior of both cell populations." (PMID 25987130, 2015). "These bone marrow-derived CCR2+/CX3CR1+ cells also co-express markers that correspond to M-MDSCs, namely, CD45+, CD11b+, Ly6Chi, and Ly6G−, migrate to glioma-secreted CCL2 and CCL7, and suppress the proliferation and IFN-γ secretion of both CD4+ and CD8+ T cells." (PMID 39272914, 2024). "We found multiple human tumor types expressed CX3CR1 with GBM (Glioblastoma), LGG (Low Grade Glioma), LAML (Acute Myeloid Leukemia), KIRC (Kidney Renal Clear Cell Carcinoma), KIRP (Kidney Renal Papillary Cell Carcinoma) having notably high expression compared with the normal tissue." (PMID 37771579, 2023). "Flow cytometry of an additional matched glioma grade 4 patient cohort confirmed an increased abundance of CX3CR1+ CD8+ T cells in PBMC compared to almost absent CX3CR1+ CD8+ T cells in tumor periphery." (PMID 38127790, 2023). "Later work comparing steady-state microglia and macrophages revealed that CX3CR1 and CCR2 might be candidate markers to distinguish these cell populations, but these markers proved unreliable in the context of glioma." (PMID 37365324, 2023). "We also saw no changes in the population of CCR2+/CX3CR1+ cells in the bone marrow of mice harboring chemokine knockdown gliomas." (PMID 36685592, 2022). "Regardless, a study using a murine model of glioma found no expression of Cx3cr1 in glioma-infiltrating T cells, nor a role for this receptor in T-cell recruitment to glioma." (PMID 35464424, 2022). "Upon validating CCR2+/CX3CR1+ cell migration to the conditioned media of KR158B and KR158B CCL2 KD glioma cell lines, we sought to determine whether the migration was exclusively mediated by CCL2 and/or CCL7." (PMID 36685592, 2022). "Our earlier studies established that CCR2+/CX3CR1+ myeloid cells, characterized by M-MDSC markers (CD45, CD11b, Ly6Chi, and lack Ly6G), are present in the bone marrow and infiltrate into multiple murine gliomas (KR158B and 005 GSC)." (PMID 36685592, 2022). "CCR2 and CX3CR1 expressing cell populations were assessed via flow cytometry within the glioma microenvironment as well as non-tumor peripheral tissues: blood, spleen, and bone marrow." (PMID 36685592, 2022). "Using a preclinical glioma model, we demonstrate that CCR2+/CX3CR1+ cells are sourced from the bone marrow, suppress both CD4+ and CD8+ T cells, migrate to CCL2 and/or CCL7 in a CCR2-dependent manner, and are reduced in the glioma microenvironment through combination targeting of CCL2 and CCL7." (PMID 36685592, 2022). "By contrast, selective ablation of Cx3cr1 in microglia had no impact on glioma growth." (PMID 29594035, 2018).
glioma (continued). "Glioma cell lines did not express CXCR3, CXCR4, CXCR6, CX3CR1, but high levels of CXCR7, which is a receptor for CXCL11 and CXCL12 and can mediate G-protein independent signals via arrestin." (PMID 26796342, 2016). "CD68 staining is confined to M/Mφ population (as verified by co-labelling with GFP+ cells in CX3CR1+/GFP mice), being completely absent in glioma cells." (PMID 25818172, 2015).
Stroke (44 papers, 2005 to 2025). Sudden impairment of blood flow to a part of the brain due to occlusion or rupture of an artery to the brain. "Conversely, CX3CR1 deficiency delays Aβ pathology in experimental models, indicating its role in promoting post-stroke Alzheimer’s-like neurodegeneration." (PMID 40722349, 2025). "Human genetic studies confirm that the CX3CR1 T280M loss-of-function polymorphism significantly elevates risk for post-stroke cognitive impairment and dementia." (PMID 40722349, 2025). "It is noteworthy that in contrast from stroke injury, CX3CR1 deficiency in AD animal models enhances Aβand Aβassociated brain pathology; and such enhanced Aβphenotypes are also observed in VPS35-deficient mice." (PMID 31771656, 2019). "The present study was performed to investigate if CX3CR1 deficiency affects microglia during the first 14 days with consequences for tissue damage after experimental stroke." (PMID 28061814, 2017). "Previous studies provided data showed that CX3CR1 deficiency affects the morphology of immune cells in the ischemic territory during the first 24 h after stroke." (PMID 28061814, 2017). "Summarizing both studies, administration of fractalkine but also CX3CR1 deficiency seem to be beneficial after experimental stroke and models of neurodegeneration." (PMID 28061814, 2017). "Similar results were observed in the acute phase after transient MCAO showing that CX3CR1 deficiency reduced ischemic damage and CX3CR1-deficient mice displayed a stroke-protective inflammatory milieu during the first 72 hours after stroke." (PMID 25881123, 2015). "Summarizing these findings, administration of FKN but also CX3CR1 deficiency seems to be beneficial in the acute phase after stroke." (PMID 25881123, 2015). "Further studies confirmed that CX3CR1 deficiency may facilitate alternative microglial cell activation after stroke, suggesting that CX3CR1 abolition attenuates microglia proliferation and inflammatory capacity, improving neurological recovery." (PMID 34831273, 2021). "In MCAO stroke model, CX3CR1-deficient mice show reductions in infarct size and neuron death." (PMID 31771656, 2019). "We also injected GFP+ monocytes deficient in Cx3cr1 into CSF of ipsilateral lateral ventricle 1 day after stroke and could still detect GFP+ MDMs in the ischemic hemisphere 3 days thereafter." (PMID 28754163, 2017). "Whereas CCR1, CCR2 and CCR5 expression was found to be unchanged, a reduced gene transcription of the microglial-associated chemokine receptor CX3CR1 was observed after stroke in TREM2-KO mice compared to littermate control mice (12 h: to 79% ±6.7; 7 d: to 50% ±4.6, p≤0.05, n = 5/6 each)." (PMID 23301011, 2013). "Finally, stroke-induced CX3CR1 protein levels are abolished in microglial VPS35-deficient mice." (PMID 31771656, 2019). "Dynamic predictive models constructed from such data can learn patient-specific temporal data streams to accurately predict individualized post-stroke CX3CR1 signaling trajectories and identify optimal intervention time windows." (PMID 40722349, 2025). "Collectively, this evidence confirms that CX3CR1-targeted stroke therapies must incorporate strict temporal specificity." (PMID 40722349, 2025). "Given the stage-dependent functional duality of CX3CR1 signaling and its dynamic evolution across stroke pathology, therapeutic interventions must adhere to strict temporal precision." (PMID 40722349, 2025). "These molecules have demonstrated utility in cancer immunotherapy and inflammatory regulation, positioning them as promising candidates for future stroke therapeutics targeting CX3CR1." (PMID 40722349, 2025). "These clinical data establish CX3CR1 signaling as a critical molecular determinant of long-term neurological prognosis after stroke." (PMID 40722349, 2025). "Nonetheless, through synthesizing cross-disciplinary evidence and contentious viewpoints, this work constructs an innovative framework for CX3CR1-targeted stroke therapeutics." (PMID 40722349, 2025).